GCHFR (GTP cyclohydrolase I feedback regulator)
Description:
Mediates tetrahydrobiopterin inhibition of GTP cyclohydrolase 1. This inhibition is reversed by L-phenylalanine.
Synonyms: GFRP; HsT16933; P35
Tractability: Small molecule: a structure with a bound ligand is known. PROTAC: ubiquitination databases record sites on it; its protein half-life has been measured.
Gene: Protein-coding gene on chromosome 15 (40,764,068 to 40,767,708, forward strand). Ensembl gene ENSG00000137880.
Subcellular location: Nucleus; Nucleus membrane; Cytoplasm, cytosol
Subcellular location (Human Protein Atlas): Nucleoplasm
Pathways (Reactome):
Metabolism: Tetrahydrobiopterin (BH4) synthesis, recycling, salvage and regulation
Gene Ontology:
Molecular function: protein binding; GTP cyclohydrolase binding; enzyme inhibitor activity
Biological process: regulation of nitric oxide biosynthetic process
Cellular component: cytoplasm; dendrite; melanosome; nuclear membrane; nucleoplasm; nucleus; cytosol
Genetic constraint (gnomAD): Loss-of-function variants: 7 observed, 4.17 expected, observed/expected ratio (o/e) 1.68, 90% interval 0.86 to 1.95. That is too few expected variants to judge how well the gene tolerates losing a copy. Missense variants: 78 observed, 64.56 expected, observed/expected ratio (o/e) 1.21, 90% interval 1 to 1.46. Synonymous variants: 37 observed, 27.65 expected, observed/expected ratio (o/e) 1.34, 90% interval 1.03 to 1.75.
Homologues: Orthologues: chimpanzee GCHFR (100% identical), guinea pig GCHFR (94% identical), mouse Gchfr (93% identical), dog GCHFR (88% identical), macaque GCHFR (86% identical), rat Gchfr (85% identical), zebrafish gchfr (73% identical), tropical clawed frog gchfr (70% identical), Caenorhabditis elegans gfrp-1 (57% identical).
Diseases named in the same sentence as GCHFR in open-access papers:
GCHFR is named in the same sentence as 8 diseases in open-access papers, as found by Europe PMC text mining. Sharing a sentence is not in itself a finding about the gene and the disease. The quoted sentences say what the papers report.
melanoma (2 papers, 2021 to 2022). A malignant, usually aggressive tumor composed of atypical, neoplastic melanocytes. "Data sets from TCGA showed increased GCH1 expression along with melanoma progression (n = 248) and decreased expression of GCHFR in melanoma (n = 461) compared with normal skin (n = 558)." (PMID 34502464, 2021). "Moreover, public data from Oncomine and TCGA showed that high GCH1 expression correlates with melanoma aggressiveness, increased expression of PTS and SPR, and decreased GCHFR expression in melanoma when compared to benign nevi." (PMID 34502464, 2021). "Since GCHFR expression is higher in WM1552C cells when compared to melanocytes (data not shown), a functional GFRP/GTPCHI axis could be the mechanism controlling the BH4 concentration in these melanoma cells, as found in melanocytes." (PMID 35682659, 2022).
bovine tuberculosis (1 paper, 2024). "Other genes found in the present study related to immunity and adaptation in literature were DNAJC17 (heat tolerance in Zebu cattle), GCHFR, MDGA2 (heat stress in cows), FOXF1, NKG7 (bovine tuberculosis response), and SIGLEC10." (PMID 39766784, 2024).
GCHFR also shares sentences with these, for which no sentence is quoted: endothelial dysfunction (2 papers); genetic disorders (1); Hypertension (1); infection (1); liver diseases (1); phenylketonuria (1).